BRCA1 (BRCA1 DNA repair associated)
Diseases named in the same sentence as BRCA1 in open-access papers (continued):
Sharing a sentence is not in itself a finding about the gene and the disease.
ovarian tumors (continued). "(2017) showed that though most breast or ovarian tumors with germline BRCA1/BRCA2 loss of function mutations respond to DNA damaging agents, some tumors do not show such a response." (PMID 29797793, 2018). "BRCA1/2 mutations, seen most commonly in familial breast and ovarian tumors, impact the DNA repair pathway leading to genomic instability." (PMID 29459887, 2018). "Increased lymphocytic infiltration in the tumor microenvironment is a histological phenotype observed in BRCA1/2-mutated ovarian tumor." (PMID 30382883, 2018). "In fact, in ovarian tumors with BRCA1 mutation, two third of the cases had germline mutation, and they were seen by genetic counselors." (PMID 28915716, 2017). "Fifty-two of 55 BRCA1 germline mutation-associated breast and ovarian tumors had locus-specific LOH, with two breast (11%) and one ovarian (3%) tumors lacking locus-specific LOH." (PMID 28831036, 2017). "Olaparib, the first PARP inhibitor approved in the clinic has proven effective in the treatment of ovarian tumours characterized by BRCA1/2 mutations and many other trials are ongoing to demonstrate the potency of other PARP inhibitors in BRCA1/2 tumours." (PMID 28800752, 2017). "PTEN loss is a common feature of breast and ovarian tumors associated with germline mutations in BRCA1 and BRCA245." (PMID 28831036, 2017). "Analysis of primary data from TCGA identified 100 breast and ovarian tumors with germline BRCA1 (n = 55) and BRCA2 (n = 45) mutations." (PMID 28831036, 2017). "We have performed an in-depth examination of the genomic profiles of primary breast and ovarian tumors in patients with germline BRCA1 and BRCA2 mutations with the goal of identifying correlates of therapeutic response, using two data sets." (PMID 28831036, 2017). "Three of 23 (13%) breast and three of 15 (20%) ovarian tumors associated with BRCA1 germline mutations, and seven of 16 (44%) breast and one of six (17%) ovarian tumors associated with BRCA2 germline mutations did not have BRCA locus-specific LOH." (PMID 28831036, 2017). "The term ‘BRCAness’ has been used to describe the phenotypic traits that some sporadic ovarian tumours share with tumours found in BRCA1/2 germline mutation carriers and reflects similar causative molecular abnormalities." (PMID 26800494, 2016). "Studies of ovarian tumours in women with BRCA1 or BRCA2 mutations have shown that BRCA1 and BRCA2 carriers predominantly develop serous disease." (PMID 27463617, 2016). "BRCA1/2 alterations of all kinds, including mutations, have been reported in up to 82% of ovarian tumours." (PMID 26800494, 2016). "Given the recent regulatory approval in the USA and Europe for olaparib (now named Lynparza) as a treatment for BRCA1/2-deficient ovarian tumours, the functional assessment and validation of candidate biomarkers is most timely." (PMID 25883215, 2015). "In the present study, the expression and methylation of BRCA1 was investigated in the same cohort of ovarian tumor patients as our previous study and the association between BRCA1 expression and methylation was analyzed." (PMID 24944674, 2014). "Similar results were observed in ovarian tumors with BRCA1/2 mutations, where BRCA1 hypermethylation predicted better response to poly(ADP)-ribose polymerase inhibitor treatment." (PMID 25473433, 2014). "Ovarian tumors from these models, including those deficient in either Brca1 or Brca2, represent all 4 transcriptional subclasses of human SEOC." (PMID 24748377, 2014). "We examined the impact of mono- or combinatorial long-term therapy on survival in a cohort that received Brca1-deficient orthotopic ovarian tumor transplants." (PMID 24748377, 2014).
ovarian tumors (continued). "Secondary mutations in the BRCA1 gene that restored open reading frame of mutated Brca1 allele have been observed in ovarian tumors with resistance to platinum." (PMID 24748377, 2014). "Another report indicated that hypermethylation of the BRCA1 promoter correlated with gene inactivation in sporadic breast and ovarian tumors, as inherited BRCA1 mutations." (PMID 23442605, 2013). "Breast and ovarian neoplasms from BRCA1 or BRCA2 mutation carriers are characterized by deficient homologous recombination (HR) of DNA, that makes them particularly sensitive to platinum compounds or inhibitors of poly (ADP-ribose) polymerase (PARP)." (PMID 21819606, 2011). "It was previously shown that when compared to sporadic cancers BRCA1-associated ovarian tumors were characterized by higher mean expression levels of genes mapped to Xp11." (PMID 15383145, 2004). "Supporting our hypothesis, 82 proteins were commonly elevated more than or equal to twofold across the BRCA1/2‐mutated and ovarian neoplasm groups over controls." (PMID 41482634, 2026). "However, validation of this variant failed in a large German cohort and in BC and ovarian tumors with BRCA1 promoter hypermethylation, indicating suggesting low allelic frequency in German and Dutch patients." (PMID 38898118, 2024). "Notably, olaparib (which is a PARP inhibitor) represents a targeted therapeutic drug that is currently employed in patients with ovarian tumors harboring BRCA-1 gene mutations, thus yielding favorable clinical outcomes." (PMID 39281319, 2024). "In this study, we assessed the utility of ovarian tumour characteristics as predictors of BRCA1 and BRCA2 variant pathogenicity, for application using the American College of Medical Genetics and the Association for Molecular Pathology (ACMG/AMP) variant classification system." (PMID 37076566, 2023). "Indeed, the loss of function mutations of BRCA1 are recurrent in familiar and sporadic breast and ovarian tumors." (PMID 37887275, 2023). "Our real-world data show a higher rate of unreported germline BRCA1/2 pathogenic variants compared to myChoice® CDx test data from breast and ovarian tumours tested in the randomised, Phase 3 PARPi trials OlympiAD and SOLO2, where the missed rate was much lower at 0.7% and 1.7%, respectively." (PMID 38201604, 2023). "Apparently, Brca1 mutations sensitize ovarian tumor cells to cisplatin-induced senescence." (PMID 35082152, 2022). "Genetic evaluation of the ovarian tumor showed two BRCA1 pathogenic variants." (PMID 34790454, 2021). "Under current guidelines, women presenting with breast or ovarian tumors are routinely tested for hereditary mutations in BRCA1/2 and this guides whether they are treated with PARP inhibitors." (PMID 33015058, 2020).
ovarian tumors (continued). "Here, we examined the diagnostic impact of combined BRCA1/2 sequence, copy number, and promoter DNA methylation analysis, and evaluated whether genomic DNA methylation patterns can predict the BRCAness in ovarian tumors." (PMID 32483276, 2020). "Two functions (cell-to-cell signaling and interaction, and cellular growth and proliferation, and two upstream regulators (TGFB1 and IFNG) were shared between differentially expressed genes in the isogenic cell lines and differentially expressed genes in BRCA1-deficient vs. normal ovarian tumors." (PMID 31840082, 2019). "Our exploratory transcriptomic analyses using TIMER predicted that dendritic cells and neutrophils as being differentially present in BRCA1-deficient vs. BRCA normal ovarian tumors, also supporting the concept that cellular immune responses are augmented in this setting." (PMID 31840082, 2019). "BRCA genes are also involved in the development of sporadic breast and ovarian tumors; and patients, carrying a germline or somatic BRCA1/BRCA2 variants, may benefit from PARP inhibitors therapy." (PMID 31065452, 2019). "However, generally speaking, it is possible to state that individuals bearing BRCA1/2 mutations have a 40–60% risk of developing breast cancer and a 20–40% risk of developing an ovarian tumor in their life." (PMID 29026449, 2017). "Indeed, ovarian tumors with BRCA1 or BRCA2 mutations, either germline or somatic, are associated with higher mutational burden and better survival outcomes following treatment with platinum-based chemotherapy or PARP inhibitors." (PMID 27959926, 2016). "Similar results have been reported for other TSGs involved in controlling genomic stability, such as the inhibition of PARP-1 in BRCA1/2 deficient breast and ovarian tumors which selectively kills the cancer cells while sparing normal cells with a functional repair pathway." (PMID 21122106, 2010). "Brca1LoxP/LoxP mice that received bilateral intrabursal Ad5-CMV-Cre injections were observed for an average of 475 days (±102 days) prior to euthanasia suggesting that conditional inactivation of Brca1 alone is insufficient to cause ovarian tumors even after long latency." (PMID 20046879, 2009). "Furthermore, BRCA1 methylation has only been found in breast and ovarian tumours and has been associated with AI at the BRCA1 locus and reduced BRCA1 gene expression." (PMID 16846527, 2006). "Additionally, 1117 genes were differentially expressed both in BRCA1-null vs. BRCA1+ OC cells and in the BRCA1-deficient vs. BRCA1-normal ovarian tumors, supporting similarity between the selected cellular model to study BRCA1 mutation-associated transcriptomic changes and human HGSOC tumors." (PMID 31840082, 2019). "In aggregate, our findings from the largest single study of breast and ovarian tumors associated with BRCA1 and BRCA2 germline mutations suggest that locus-specific LOH may be a biomarker for a BRCAness phenotype in whole tumor formalin-fixed paraffin embedded (FFPE) specimens." (PMID 28831036, 2017). "An alternative explanation for the lack of epithelial cancers in this model comes from several recent studies suggesting the precursor lesion of ovarian tumors arising in BRCA1 mutation carriers may reside in the fallopian tube rather than the ovarian surface epithelium." (PMID 20046879, 2009). "Pathogenic/likely pathogenic germline variants in the BRCA1 and BRCA2 genes are associated with an increased risk of developing cancer, particularly breast and/or ovarian tumors." (PMID 39980563, 2025). "The decreased ATP levels from BRCA1 depletion are mainly due to NNMT upregulation, making NNMT a potential therapeutic target in BRCA1-deficient ovarian tumors." (PMID 39272943, 2024). "Routine molecular profiling for deleterious germline variants in BRCA1 and BRCA2 has become an integral component of the diagnostic and therapeutic approach to hereditary breast and ovarian neoplasms." (PMID 39796670, 2024).
ovarian tumors (continued). "The first developed RAD51-based HRD test, the REcombination CAPacity (RECAP) test, has shown a high sensitivity in identifying breast and ovarian tumors with PVs in BRCA1/2 or BRCA1 promoter hypermethylation." (PMID 37725154, 2023). "Histology associations with BRCA1 and BRCA2 variant pathogenicity were further refined by performing the LR analyses in combination with other ovarian tumour characteristics." (PMID 37076566, 2023). "We provide detailed estimates for predicting BRCA1 and BRCA2 variant pathogenicity based on ovarian tumour characteristics." (PMID 37076566, 2023). "To evaluate if LOH can be an effective predictor of BRCA1 variant pathogenicity, we carried out LOH analysis on DNA extracted from 90 breast and seven ovary tumors diagnosed in 27 benign and 55 pathogenic variant carriers." (PMID 35039532, 2022). "For instance, it has been demonstrated that BRCA1 deficiency upregulates N-nicotinamide methyltransferase (NNMT), which mediates metabolic reprogramming and sensitizes ovarian tumor cells to mitochondrial metabolic targeting agents." (PMID 36147929, 2022). "Another important function of USP13 is that it promotes the DNA damage response in ovarian tumor cells by recruiting the BRCA1/RAP80 complex to DNA damage sites." (PMID 36564767, 2022). "Loss of heterozygosity was observed for 8 informative SNPs in the BRCA1 gene in the ovarian tumour tissue, in support of BRCA1 being involved as evidence of a larger ‘second hit’ in tumorigenesis." (PMID 36068545, 2022). "Mechanistically, BRCA1 depletion leads to metabolic adaptation of ovarian tumor cells by reducing mitochondrial respiration and ATP production." (PMID 36147929, 2022). "The efficiency of PARP inhibitors was first related to pathogenic alterations in BRCA1 and BRCA2, but homologous recombination deficiency (HRD) has since been proven to sensitize ovarian tumors to PARP inhibitors as well." (PMID 34206535, 2021). "A recent meta‐analysis showed that on average only 16.3% (430/2636) of all reported primary ovarian tumors are showing signs of BRCA1 promoter hypermethylation, but that hypermethylation is strongly correlated with high‐grade serous carcinomas." (PMID 34601813, 2021). "This is best illustrated by the requirement of POLQ for the survival of BRCA1/2 mutant cancer cell lines, and the upregulation of POLQ in BRCA1/2 deficient breast and ovarian tumors." (PMID 33750946, 2021). "Overall, the rate for germline BRCA1 or BRCA2 mutations is relatively low with 4–6% of breast and 8–15% of ovarian tumors expressing one of these mutations." (PMID 33669749, 2021). "The identification of alterations in BRCA1/2 genes represents a fundamental step in the early diagnosis and treatment of breast and/or ovarian tumors." (PMID 34068254, 2021). "BRCA1 promoter hypermethylation was first shown in sporadic breast and ovarian tumors more than 20 years ago." (PMID 34601813, 2021). "BRCA1 and BRCA2 genes are the most common genes defined in literature with certain mutations and lead to an increased risk of breast and ovarian neoplasms." (PMID 34653224, 2021). "According to studies, oncogenic miR-182 expression is upregulated in high-grade ovarian tumors, resulting in proliferation and progression of cancer cells by enhancing the BRCA1/HMGA2 dysregulation." (PMID 34721577, 2021). "It is now well established that cancers that exhibit pathogenic variants in BRCA1 or BRCA2 respond well to treatment with PARPi, a therapeutic strategy that has emerged for BRCA1- and BRCA2-mutated breast and ovarian tumors." (PMID 33195396, 2020). "By comparison, 110 genes were differentially expressed genes between BRCA1- and BRCA2-associated ovarian tumours." (PMID 33081408, 2020). "Genomic DNA methylation data can partially predict BRCAness in ovarian tumors; however, further investigation in expanded BRCA1/2 cohorts is needed, and the effect of other double strand DNA repair gene defects in these tumors warrants further investigations." (PMID 32483276, 2020).
ovarian tumors (continued). "When TCGA tumors were stratified by mutation and tumor type, both BRCA1 and BRCA2 germline mutation-associated breast and ovarian tumors had a significantly higher proportion of BRCA signature (Signature 3) compared to nonBRCA breast and ovarian tumors." (PMID 28831036, 2017). "Herein we report analyses of 160 BRCA1 and BRCA2 germline mutation-associated breast and ovarian tumors." (PMID 28831036, 2017). "Patients with BRCA1-IRIS overexpressing ovarian tumors have also been shown to have shorter survival compared with cases with low BRCA1-IRIS expressing tumors." (PMID 27489859, 2016). "We recently showed BRCA1-IRIS overexpression promotes intrinsic as well as acquired cisplatin resistance in ovarian tumor and HOSE cells, respectively." (PMID 25583261, 2015). "We identified 34 BRCA1 hypermethylated ovarian tumors characterized by both promoter hypermethylation and reduced expression of BRCA1." (PMID 25437005, 2014). "The methylation of BRCA1 was detected in 142 cases of malignant tumors and 32 cases of benign, ovarian tumors." (PMID 24944674, 2014). "Complete or partial inactivation of the BRCA1 gene through hypermethylation of its promoter has been reported in 15% of sporadic ovarian tumors." (PMID 24821107, 2014). "In the present study, the tissue sections were obtained from 174 ovarian tumor samples for the evaluation of BRCA1 protein expression and promoter methylation." (PMID 24944674, 2014). "Hypermethylation leads to the silencing of this gene in ovarian tumors and levels of methylation correlated with decreased BRCA1 expression." (PMID 24821107, 2014). "Studies have identified an inverse correlation between ID4 and BRCA1 mRNA and protein expression levels in breast and ovarian tumour tissue." (PMID 21854619, 2011). "BRCA1 and BRCA2 mutated ovarian tumors have different gene expression profiles, however, the gene expression profile of sporadic ovarian tumor overlaps with both." (PMID 20843305, 2010). "Imbalance of BRCA1/2 related ovarian tumors in the arms of a randomized trial will introduce a powerful bias." (PMID 19825178, 2009). "Several studies have reported hypermethylation of the BRCA1 promoter in sporadic breast and ovarian tumours." (PMID 16846527, 2006). "Like BRCA1 and BRCA2, therefore, it appears that LKB1 mutations can cause ovarian tumours when present in the germline, but occur rarely in the soma." (PMID 10389980, 1999). "An example was the discovery of mutations in the BRCA1 and BRCA2 genes which entail a substantial increase in the risk of developing cancers, mainly breast and ovarian neoplasms, often leading to drastic preventive decisions such as prophylactic mastectomy and/or oophorectomy." (PMID 40863452, 2025). "The breast and ovarian tumor suppressor BRCA1 is a cell cycle-regulated protein and tumors with reduced BRCA1 protein level may share molecular features of BRCA1-mutant tumor and respond to PARPi therapy." (PMID 41359628, 2025). "Our results obtained with the 44-gene panel do not seem fully consistent with the literature, as we found variants in BRCA1/2 genes in many non-high-grade ovarian tumors." (PMID 39456660, 2024). "The distribution of ovarian tumour characteristics differs between germline BRCA1 and BRCA2 pathogenic variant carriers and non-carriers." (PMID 37076566, 2023). "One exception is alterations in DNA damage repair (DDR) genes, especially BRCA1/2, since BRCA-associated tumors, including breast, prostate and ovarian tumors, respond to poly–(adenosine diphosphate–ribose) polymerase (PARP) inhibitors and platinum-based therapy." (PMID 36139606, 2022). "The levels of tumor-infiltrated CD8+ T cells in the HGSOC tumors reveal a positive correlation with the patients’ survival regardless of the extent of residual disease, therapy, or BRCA1 mutation." (PMID 33968933, 2021).